TERT (telomerase reverse transcriptase)
Diseases named in the same sentence as TERT in open-access papers (continued):
Sharing a sentence is not in itself a finding about the gene and the disease.
melanoma (continued). "Survival predictions are currently determined on the basis of NRAS/BRAF mutations, even though TERT promoter mutations have been recently associated with a poor prognosis in stage I-II melanomas." (PMID 30934988, 2019). "TERT core promoter mutations at the somatic level have been well described as main responsible for telomerase activation in melanoma and BCC, while only few studies analysed cSCC." (PMID 30884806, 2019). "Mutations in the TERT promoter have been identified in >70% of melanomas, constituting the most frequent genetic alteration in these tumors." (PMID 29695835, 2018). "Of note, TERT levels were downregulated following NRAS depletion in both NRAS-mutant melanoma cells harboring TERT promoter mutations and to a lesser degree in melanoma cells with wild-type TERT promoter." (PMID 29695835, 2018). "TERT promoter mutations are key drivers of telomerase reactivation in cancer and in melanoma in particular." (PMID 30166456, 2018). "In 2013, somatic hotspot mutations in the promoter region of TERT were reported among patients with melanoma." (PMID 29222734, 2018). "TERT gene promoter variants in melanoma patients that generate binding sites for Ets/TCF transcription factors are “variation at intergenic DNA” (VariO:0163)." (PMID 30591019, 2018). "The three latter genes are involved in telomere biology together with TERT which was also found to predispose to melanoma." (PMID 29963229, 2018). "According to the TCGA data analysis, TERT promoter mutations frequently occur in melanoma, mainly in the BRAF (75% of cases), RAS (72% of cases), and NF1 (83% of cases) subtypes, suggesting a link between MAPK activation and TERT expression." (PMID 30166456, 2018). "In these types of cancer other than melanoma, C228T and C250T were also hotspots of TERT promoter mutations, in which C228T is more dominant than C250T." (PMID 29222734, 2018). "With respect to the TERT locus, an extensive sequencing of the gene and its promoter in pigs is required to search for mutations similar to the ones observed in melanoma and other human cancers." (PMID 29963229, 2018). "The discovery of TERT promoter mutations in most melanomas has provided compelling evidence that this gene has a critical role in this disease, and, therefore, constitutes a promising therapeutic target." (PMID 29695835, 2018). "For example, whole-genome sequencing of several malignant melanomas showed that in 17 of 19 cases analyzed mutations (C228T and C250T) were found within the telomerase reverse transcriptase (TERT) promoter." (PMID 29922517, 2018). "Two pioneering studies showed that mutations present in the telomerase reverse transcriptase (TERT) promoter in tumor samples of patients with melanoma lead to increased TERT mRNA expression." (PMID 29456552, 2018). "Here we describe and validate a method to detect the two most common TERT promoter mutations found in melanoma tumors using ddPCR." (PMID 29108273, 2017). "RNA of a sufficiently high quality for reverse transcription and quantitative PCR (RT-qPCR) analysis was extracted from 14 of 19 conventional melanomas (8 with mutated TERT promoter; 6 with wild-type TERT promoter), 1 nevoid melanoma, and 4 spitzoid melanomas." (PMID 28378855, 2017). "These considerations suggest that TERT promoter mutations are important driver events and contribute to melanoma tumorigenesis." (PMID 29156643, 2017). "TERT promoter mutations when combined with BRAF/NRAS mutations correlate with adverse outcome in adult melanoma." (PMID 28378855, 2017). "Our study replicates 20 of 21 previously known melanoma-loci and confirms the association of the telomerase reverse transcriptase, TERT, with melanoma susceptibility at genome-wide significance." (PMID 28212542, 2017). "Sequencing of the TERT promoter revealed that 10 of 19 (53%) conventional melanomas harbored promoter mutations (3 cases of −124C > T and 7 cases of −146C > T)." (PMID 28378855, 2017).
melanoma (continued). "Polymorphisms at the TERT locus have been associated with melanoma in multiple candidate studies and rare mutations in TERT have been identified in high-incident melanoma families." (PMID 28212542, 2017). "Recently, recurrent mutations in the promoter region of TERT were detected in 70% of malignant melanomas." (PMID 29262650, 2017). "We validated μ-cisTarget by re-analyzing the TAL1 and LMO1 enhancer mutations in T-ALL, and the TERT promoter mutation in melanoma." (PMID 28854983, 2017). "TERT promoter mutations are common in various cancers and found in up to 70% of melanomas, including half of BRAF wild-type cases." (PMID 29108273, 2017). "Recurrent somatic mutations in the TERT promoter were found in cancers of the central nervous system (43%), bladder (59%), thyroid (follicular cell-derived, 10%) and skin (melanoma, 29%)." (PMID 29100407, 2017). "Although a larger cohort is necessary to confirm these findings, they nevertheless highlight the need for a comprehensive understanding of the of TERT dysregulation in AYA melanoma to develop prognostic assays for clinical risk stratification." (PMID 28378855, 2017). "This revealed that only three samples had enough coverage to detect the TERT promoter mutation; thus, we used these three melanoma samples to predict candidate cis-GoF mutations." (PMID 28854983, 2017). "TERT promoter mutations occur in melanoma as frequently as, or more frequently than BRAF mutations, and yet mainly BRAF mutant specific cfDNA is being used to monitor melanoma patients for response to therapy and disease progression." (PMID 29108273, 2017). "This was apparent by the results obtained from 9 cell lines with known TERT promoter dinucleotide mutations C227T/C228T and C241T/C242T, which have been reported to exist in 5.2% and 10.4% of primary melanomas respectively." (PMID 29108273, 2017). "Since the discovery of predisposing variants in TERT promoter, research on melanoma genetics has focused on germline mutations in genes coding for components of the telomere maintenance complex." (PMID 29081790, 2017). "We selected seven melanoma samples from TCGA with a TERT promoter mutation and for which expression and whole genome mutation data are available through TCGA." (PMID 28854983, 2017). "Sequence variants located within, or immediately adjacent to the TERT gene, are strongly associated with several cancers, notably melanoma, breast, bladder and prostate cancers." (PMID 28454108, 2017). "TERT promoter mutation and/or methylation was significantly more common in conventional melanoma than in spitzoid or nevoid melanoma (P = 0.001)." (PMID 28378855, 2017). "Our GWAS found an association between the TERT marker rs139996880 (5p15.33) and increased melanoma risk at genome-wide significance (P = 7.16 × 10−12; OR = 1.26) confirming the association of TERT with melanoma." (PMID 28212542, 2017). "We also determined the sensitivity and specificity of this assay for the detection of TERT promoter mutations using plasma derived cfDNA from 56 melanoma patients and 56 healthy controls." (PMID 29108273, 2017). "A recent study better clarified the role of TERT promoter mutations during the evolution of genetic abnormalities leading to melanoma development." (PMID 29156643, 2017). "Several such TERT promoter mutations, that significantly increase telomerase expression, have been identified in melanomas and several other tumors." (PMID 28454108, 2017). "As such, routine genetic testing of melanoma patients for TERT promoter mutations in addition to mutant BRAF and NRAS would be clinically beneficial." (PMID 29108273, 2017). "In 41% of acral melanoma patients, TERT aberrations were observed, encompassing point mutations, breakpoints, copy gains, and coding germline mutations." (PMID 29156643, 2017).
melanoma (continued). "First, we tested the concordance of this assay for the detection of TERT promoter mutations in 39 melanoma cell lines relative to Sanger sequencing, and in 22 plasma samples relative to patient matched tumor tissue." (PMID 29108273, 2017). "In 2013, a promoter mutation was discovered in the telomerase reverse transcriptase (TERT) gene in melanoma patients." (PMID 26992833, 2016). "We tested for the TERT promoter variant in 675 multicase families wild-type for the known high penetrance familial melanoma genes, 1863 UK population-based melanoma cases and 529 controls." (PMID 26433962, 2016). "In melanoma, those somatic mutations have been associated with increased TERT expression, increased Breslow thickness, tumor ulceration, and poor disease-free and melanoma-specific survival." (PMID 27449293, 2016). "The TERT promoter mutations were also found to occur as somatic alterations at a high frequency in melanoma tumors from unrelated patients." (PMID 27449293, 2016). "In this communication, we report that TERT expression is dependent of MAPK pathway activation only in melanoma cell lines carrying the TERT promoter mutations." (PMID 27449293, 2016). "Somatic mutations in the TERT promoter were first identified in melanoma and have been observed at high frequency in multiple cancer types, including those of the thyroid, central nervous system, and bladder." (PMID 27852061, 2016). "In this report, we describe the contribution of inherited TERT promoter mutations to melanoma susceptibility by screening samples from 675 melanoma families consisting of 273 with 3 or more cases and 402 with 2 cases of melanoma." (PMID 26433962, 2016). "We investigated the regulation of TERT expression in melanoma cell lines and our results show that promoter mutations render TERT expression dependent on MAPK activation due to oncogenic BRAF or NRAS mutations." (PMID 27449293, 2016). "The identification of POT1 and TERT germline mutations highlights the importance of telomere integrity in melanoma biology." (PMID 26433962, 2016). "In 2013, specific high frequency promoter mutations in the telomerase reverse transcriptase (TERT) gene in melanoma were reported, and were associated with a two- to four-fold increase in transcriptional activity." (PMID 27792139, 2016). "We provide evidence confirming that a rare promoter variant of TERT (c.−57 T>G) is associated with high penetrance, early onset melanoma and potentially other cancers, and explains <1 % of UK melanoma multicase families." (PMID 26433962, 2016). "In the two TERT mutation positive families, there are a large number of melanoma cases and other cancers." (PMID 26433962, 2016). "We identified the previously reported c.−57 T>G TERT promoter variant in a single 7-case family from the UK, providing further support for this germline mutation being a very rare high penetrance melanoma susceptibility allele." (PMID 26433962, 2016). "In 2013, two seminal papers reported recurrent mutations of the TERT core promoter in both sporadic and familiar malignant melanomas." (PMID 27438857, 2016). "TERT promoter mutations at sites − 57, − 256, or − 228 are associated with melanoma, non-small cell lung cancer and bladder cancer, respectively." (PMID 27191258, 2016). "The TERT promoter mutation occurs in up to 80% of melanomas, establishing it as the commonest somatic mutation in this malignancy." (PMID 27611953, 2016). "For example, both of the landmark studies of TERT promoter mutations in melanoma used luciferase reporter assays to show increased activity of mutant over wild-type sequences." (PMID 26356674, 2015). "With the exception of melanoma where the –146C > T mutation is more frequent than any other base change in the TERT promoter, in most other malignancies –124 C > T has been reported to be the most common alteration." (PMID 25797251, 2015).
melanoma (continued). "GWAS analysis identified a specific set of TERT promoter mutations in melanomas that all occur in a very small region close to the transcriptional start site and each results in novel putative TTCCGG- ETS binding sites." (PMID 26194807, 2015). "We observed statistically significant associations with melanoma for two lung cancer SNPs in the TERT-CLPTM1L locus (Bonferroni-corrected p<2.8x10-4), replicating known pleiotropic effects at this locus." (PMID 25789475, 2015). "Somatic mutations in the coding region of TERT are infrequent in human tumors, but germ line genetic variants and somatic mutations in the TERT promoter is frequently found in human melanomas and also other human cancers and cell lines." (PMID 26143636, 2015). "The other three of these SNPs showed a decreased risk of melanoma: two TERT/CLPTM1L SNPs previously associated with lung cancer (rs402710, OR = 0.87; rs31489, OR = 0.89) and one ABO SNP previously associated with pancreatic cancer (rs505922, OR = 0.89)." (PMID 25789475, 2015). "A germline mutation (chr5:1,295,161 T > G) was also found in the TERT promoter which segregated disease in individuals in a melanoma-prone family." (PMID 26356674, 2015). "Analyses of whole-genome sequencing data from malignant melanomas revealed two somatic TERT gene promoter mutations." (PMID 26143634, 2015). "Several recent studies showed that TERT core promoter mutations occur in melanoma and other cancers." (PMID 26143634, 2015). "The two SNPs demonstrating a significant association with melanoma (rs401681 and rs4975616) are located in the TERT-CLPTM1L locus, which contains variants associated with a number of different cancers." (PMID 25789475, 2015). "SNPs in the TERT gene and amplification in its promoter have been to linked to melanoma risk in recent studies." (PMID 25612317, 2015). "In summary, we provided confirmatory evidence of pleiotropic associations with melanoma for two SNPs in TERT-CLPTM1L and identified a potentially novel sex-specific association for a SNP near TPCN2/MYEOV." (PMID 25789475, 2015). "TERT promoter mutations were found to have a UV signature and to lead to an increased TERT gene expression, being associated with poor prognosis in melanoma patients." (PMID 26322273, 2015). "We replicated previously reported associations with melanoma for two SNPs in the TERT-CLPTM1L region." (PMID 25789475, 2015). "Because TERT promoter (TERT-p) mutations are common in inherently aggressive cutaneous conventional melanoma, we sought to evaluate their prognostic significance in spitzoid neoplasms." (PMID 26061100, 2015). "Recently, recurrent mutations in regulatory DNA regions, such as promoter mutations in the TERT gene were identified in melanoma." (PMID 26327518, 2015). "Most notably, polymorphisms in or around TERT (encoding telomerase reverse transcriptase) are strongly associated with various cancers, including breast, bladder and prostate cancers and melanoma." (PMID 25986438, 2015). "Potentially the most relevant such mutation identified to date was the finding of TERT promoter mutations in a large proportion of melanoma samples (30–70%)." (PMID 26327518, 2015). "The TERT promoter harbors two recurrent mutations and these are among the highest recurring mutations in cancer (between 33% and 85% in melanoma)." (PMID 26562774, 2015). "TERT promoter mutations are not limited to melanoma, and were found in 16% of tumor cell lines from diverse cancers." (PMID 24743024, 2014). "Recently, two studies reported a high frequency (approximately 70%) somatic mutation in the TERT promoter in melanoma at positions 1,295,228 (C228T) and 1,295,250 (C250T)." (PMID 25042800, 2014). "Up to 80% of malignant melanoma harbor TERT promoter mutations and UV irradiation was proposed to result in these mutagenic lesions." (PMID 25301727, 2014).
melanoma (continued). "More recently, somatic TERT promoter mutations namely C228T and C250T have been identified as novel gain-of-function genetic events in up to 80% of malignant melanoma and other kinds of cancer." (PMID 25301727, 2014). "Mutations in the promoter region of TERT are considered to be driver mutations because of their association with familial melanoma and high frequency in sporadic melanoma." (PMID 24743024, 2014). "TERT promoter mutations, originally be discovered in ~70% melanoma, have also been found to be the most common genetic mutations of UC." (PMID 25042800, 2014). "Point mutations within the telomerase reverse transcriptase (TERT) promoter enhance TERT expression in melanoma, and in cancers of the central nervous system, bladder and thyroid." (PMID 25473436, 2014). "While a large majority of causal variants and driver mutations fall within these regions, DNA-WES will miss possibly important variants in other regions, such as a highly recurrent mutation in the promoter region of TERT in melanoma tumors." (PMID 23935067, 2013). "Recently, a germline mutation in the promoter of the TERT gene has been shown to explain melanoma susceptibility in a very large melanoma kindred which was also implicated in sporadic melanomas." (PMID 23796690, 2013). "In this study, we demonstrate that TERT promoter mutations, initially described in melanoma, comprise the most recurrent mutation described so far across medulloblastoma subgroups, with a particular enrichment in older patient cohorts." (PMID 24174164, 2013). "Recently, a melanoma-segregating germline mutation in the promoter of the telomerase reverse transcriptase (TERT) gene has been shown to create a new binding motif for Ets/TCF transcription factors such as ELK1 and ELK4, near the transcription start." (PMID 24416617, 2013). "Amongst these, ABCB1, DNMT3B, EPAS1, JARID1B and TERT have previously been designated as melanoma CSC(-associated) markers (and reviewed in 13)." (PMID 24098529, 2013). "The TERT locus has also been associated with melanoma in GWAS analyses which further support the role of the telomere unit and possibly longevity for this tumour." (PMID 23796690, 2013). "Previously, among the telomere-related genes, two SNPs in TERT, rs2853676 and rs2242652, were reported to have a significant association with melanoma in a Caucasian population." (PMID 23300679, 2012). "Such cases may reflect melanomas arising through less mutation-dependent mechanisms, or through copy-number changes, structural variation, epigenetic alteration, TERT promoter mutations, or mutations outside the panel’s coverage." (PMID 41516405, 2026). "The restricted panel breadth prevents detection of broader genomic alterations, including copy-number changes, structural variants, TERT promoter mutations, and mutations in genes outside the targeted set, which may contribute to melanoma progression." (PMID 41516405, 2026). "Somatic variants in TERT are common in melanoma, with an incidence of 68% in primary melanomas." (PMID 40558591, 2025). "Additionally, mutations in TERT promoter genes occur frequently in a variety of malignancies, including melanomas, and when detected, suggest the capability of infinite cell growth and therefore more aggressive behavior." (PMID 40933634, 2025). "However, Thielmann CM's research shows that TERT promoter mutations are associated with longer asymptomatic survival in BRAF mutant melanoma patients treated with BRAF and MEK inhibitors." (PMID 39871386, 2025).